KLF5 (KLF transcription factor 5)
Diseases named in the same sentence as KLF5 in open-access papers (continued):
Sharing a sentence is not in itself a finding about the gene and the disease.
breast carcinoma (continued). "Since ATXN3L stabilizes KLF5 and inhibits the expression of p27 and p21, it is plausible that ATXN3L also promotes breast cancer cell proliferation." (PMID 26079537, 2015). "Our findings uncovered a new regulatory mechanism for KLF5 and suggest that ATXN3L is a potential therapeutic target for breast cancer treatment." (PMID 26079537, 2015). "In summary, our study identified ATXN3L as a KLF5 DUB in breast cancer and found that ATXN3L stabilized the KLF5 protein and promoted cell proliferation partially through KLF5." (PMID 26079537, 2015). "In this study, we discovered a novel positive regulatory mechanism for KLF5 and the functional mechanism by which BAP1 promotes breast cancer growth and metastasis." (PMID 26419610, 2015). "Using tumor cells derived from this model as well as human breast cancer cells, suppression of KLF4 and/or KLF5 sensitized HER2-overexpressing cells to lapatinib." (PMID 25789974, 2015). "KLF5 and YAP1 were reported to be predominately expressed in ER- cell lines and all experimental data was obtained from ER- breast cancer cell lines." (PMID 24559095, 2014). "Furthermore, KLF5 activates CXCR4 transcription, triggering the EMT and driving the liver metastasis of breast cancer." (PMID 40740236, 2025). "We analyzed breast cancer samples from public databases and found no notable differences in KLF5 expression between the residual disease (RD) and pathological complete response (pCR) groups after neoadjuvant chemotherapy in all breast cancer samples." (PMID 37588224, 2024). "Furthermore, in breast cancer cells, PRMT5 methylates KLF5 and inhibits its phosphorylation, ubiquitylation, and degradation." (PMID 38791992, 2024). "The TCGA database showed that KLF5 mRNA was overexpressed in breast cancer, especially in HER2‐positive and triple‐negative breast cancer, the two subtypes with the highest probability of metastasis." (PMID 36529697, 2023). "KLF5 was coexpressed with basal markers (KRT5, KRT14 and KRT17) in breast cancer tissue." (PMID 36923542, 2023). "In addition to KLF5, AXL is an EMT-induced regulator of cancer metastasis, controlled by Slug and Vimentin in breast cancer." (PMID 36042208, 2022). "Meanwhile, KLF5 could upregulated CXCR4 transcriptionally to accelerate epithelial and mesenchymal transition of breast cancer." (PMID 36224562, 2022). "Our result also found that overexpression of LINC00152 significantly facilitated the proliferation of breast cancer cell, whereas knockdown of KLF5 did not induce cancer cell proliferation." (PMID 33842324, 2021). "The correlation between KLF5 and LINC00152 in breast cancer was largely unclear." (PMID 33842324, 2021). "To explore the correlation between the LINC00152-KLF5 loop and those proteins, we tried to determine whether LINC00152 or KLF5 affected the expression of PTEN or β-catenin in breast cancer cells." (PMID 33842324, 2021). "According to this study, Ataxin-3L would antagonize ubiquitination and proteasome-mediated degradation of KLF5, which means this DUB’s inhibiting activity may be a potential therapeutic target for breast cancer intervention." (PMID 32982735, 2020). "Kruppel-like factor 5 (KLF5) is an important transcription factor, which inhibits cell proliferation, differentiation and carcinogenesis, and its levels are decreased in cancers including breast cancer." (PMID 30337927, 2018). "Lineage associated transcription factors include MITF for the melanoma cell line SK-MEL-5, TP63 for the lung cancer line A549, KLF5 for the colon cancer line HT-29, and ETS family transcription factors for prostate, colon, ovarian, and breast cancer cell lines." (PMID 28854983, 2017). "To further confirm whether BAP1 increases KLF5 protein stability, we transfected two different siRNAs targeting different regions of BAP1 into MCF10A and breast cancer cell lines (HCC1806 and HCC1937)." (PMID 26419610, 2015).
breast carcinoma (continued). "Previous studies showed that KLF5 is highly expressed in estrogen receptor (ER)α-negative basal-type breast cancer." (PMID 26079537, 2015). "Alongside the transcription factors KLF5 and TEADs, further evidence also suggests that both YAP and TAZ may act as oncoproteins, promoting breast cancer tumorigenesis and metastasis." (PMID 25970772, 2015). "Furthermore, YAP1 was recently reported to function as an oncogene by promoting proliferation and survival of breast cancer cells by binding and stabilising the KLF5 (Kruppel-like factor 5) transcription factor through its PPxY motif." (PMID 24559095, 2014). "However, the TFs such as KLF5 (52%), KLF1 (39%), and SMAD2::SMAD3::SMAD4 (31%) showed significant enrichment (q < 0.1) in gained peaks and FOX family of TFs (FOXA1 28%, FOXA2 28% and FOXF2 17%) in lost peaks in breast carcinomas." (PMID 34090364, 2021). "KLF5 typically supports proliferation in nontransformed cells, providing a growth advantage, and has been shown to induce cisplatin resistance in breast cancer." (PMID 30478887, 2019). "Since high KLF5 mRNA and protein levels have been reported as a potent biomarker for unfavourable prognosis for breast cancer patients, we tried to test whether BAP1 can also serve as a biomarker for prognosis for breast cancer patients." (PMID 26419610, 2015). "BAP1 and KLF5 promote breast cancer migration, invasion and metastasis may not through p27; however, KLF5 is a transcription factor regulating numerous downstream target genes, such as FGF-BP and mPGES1." (PMID 26419610, 2015). "Since KLF5 was identified as an oncogenic molecule in intestinal cancer and estrogen receptor (ER)-negative breast cancers, curcumin or its derivatives may also be applied to these cancers to manipulate the KLF5 levels." (PMID 25170806, 2014). "However, high expression of KLF5 in breast cancer samples was directly correlated with cell proliferation in vivo and with HER-2 expression level whereas patients had a shorter disease-free survival and overall survival time than those with lower KLF5 expression." (PMID 20126619, 2010). "It deubiquitinates Krüppel-like factor 5 (KLF5), which is highly expressed in ERα-negative basal subtype breast cancers." (PMID 35884607, 2022). "We first tested the expression of p-CREB, p-GSK3β, KLF5 and FGF-BP1 in a panel of breast cancer cell lines and found that p-CREB and p-GSK3β, KLF5 and FGF-BP1 are weakly or not expressed in non-TNBC cell lines compared with HCC1937." (PMID 28480051, 2017). "In the GOBO database, lower KLF5 expression was significantly correlated with the Basal B subtype (which includes MDA-MB-231 and Hs578t) and the overall TN status but not with the Basal A status in breast cancer cell lines." (PMID 30206215, 2018). "Interestingly, depletion of either BAP1 or KLF5 did not significantly inhibited DNA synthesis in MDA-MB-231, which is a KLF5-negative breast cancer cell line." (PMID 26419610, 2015).
prostate carcinoma (63 papers, 2010 to 2025). A carcinoma that arises from epithelial cells of the prostate gland. "To understand the underlying mechanisms by which deacetylation of Klf5 promotes Pten-deficient prostate cancer progression, we performed RNA-Seq to identify differentially expressed genes (DEGs) in Pten-null mouse prostates with or without Klf5KR knockin." (PMID 38781024, 2024). "Deacetylation of KLF5 in prostate cancer cells stimulated inflammatory cancer-associated fibroblasts (iCAFs) through TNF-α to release FGF9, which in turn activated FGFR1 signaling in prostate cancer cells." (PMID 38781024, 2024). "The expression level of Cx3cr1 was increased by Klf5KR knockin in Pten-deficient prostate cancer, as suggested by RNA-Seq and confirmed by IHC staining of prostate tissues from PBCrePten–/–Klf5KR/KR and PBCrePten–/–Klf5+/+ mice." (PMID 38781024, 2024). "The overactivated FGFR1 signaling in Ac-Klf5–deficient and Pten-null prostate cancers can be attributed at least partly to the increased expression of FGF9." (PMID 38781024, 2024). "Interruption of Klf5 acetylation promoted tumor growth in Pten-deficient prostate cancer, as indicated by larger tumor sizes and enhanced cell proliferation." (PMID 38781024, 2024). "This study deciphered paracrine reciprocal communication between Pten-deficient prostate cancer cells and iCAFs coordinated by Ac-KLF5." (PMID 38781024, 2024). "Interruption of Klf5 acetylation in Pten-deficient prostate cancer cells signaled iCAFs through TNF-α to promote FGF9 release, which in turn activated FGFR1 signaling in prostate cancer cells." (PMID 38781024, 2024). "The addition of AZD8797 and JMS-17-2 selectively suppressed the growth of organoids with deAc-KLF5, indicating that induced Cx3cr1 by Klf5KR knockin is an essential mechanism by which Pten-deficient prostate cancer cells have an advantage in tumor growth." (PMID 38781024, 2024). "KLF5 downregulation is associated with unfavorable prognosis and decreased sensitivity of prostate cancer cells to docetaxel." (PMID 35317831, 2022). "In prostate cancer or another subset of bladder cancer, long segment deletion of chromosome 13q accounted for the loss of KLF5." (PMID 33923166, 2021). "KLF5 is frequently deleted and downregulated in prostate cancer, and recently it has been reported that KLF5 loss is enriched in the aggressive branches of prostate cancer evolution." (PMID 32546700, 2020). "We found that KLF5 down-regulation was associated with progression of prostate cancer and poor prognosis of patients." (PMID 31534497, 2019). "These in vitro assays provide another line of evidence for the role of KLF5 in angiogenesis in PTEN-deficient prostate cancer cells." (PMID 25896712, 2015). "Genetic amplification and overexpression of the WWP1 E3 ubiquitin ligase, which degrades KLF5 protein, also frequently occur in human prostate cancer, causing excess protein degradation and insufficiency of KLF5." (PMID 25896712, 2015). "Seems to be contradictory, a latest study in prostate cancer reported that KLF5 inhibited angiogenesis in PTEN-deficient prostate cancer by attenuating Akt activation and subsequent HIF1-maintained VEGFA expression." (PMID 26544730, 2015). "Given the robust activation of TGF-β in PTEN-deficient prostate cancer, we tested whether KLF5 acetylation at K369 is affected by PTEN/PI3K/p-AKT signaling." (PMID 38781024, 2024). "Knockin of the Klf5KR mutant successfully interrupted Klf5 acetylation in Pten-deficient mouse prostates, providing an ideal model with which to test how Klf5 acetylation affects Pten-deficient prostate cancer." (PMID 38781024, 2024). "Moreover, PI3K/AKT pathway and expression of HIF-1α, VEGF, PDGF-A, and PDGF-B are activated by KLF5 loss and blocked by KLF5 overexpression in PTEN-deficient prostate cancer." (PMID 33493334, 2021).
prostate carcinoma (continued). "Among these, we focused our attention on KLF5 because several putative KLF5‐binding sites are present in the Sp1 promoter region and because a KLF5 deletion was already linked to Sp1 upregulation in a model of prostate cancer progression." (PMID 34062049, 2021). "Interestingly, we also found that KLF5 expression was obviously lower in prostate cancer metastases than in localized tissues, indicating that KLF5 downregulation is associated with prostate cancer invasion and metastasis." (PMID 32546700, 2020). "Low KLF5 expression was associated with high Gleason Score of prostate cancer." (PMID 31534497, 2019). "Also, not only the low expression of KLF5 but the low level of KLF5/high level of BECN1 are associated with the poor prognosis of prostate cancer patients and have a potential value in precision medicine for the prognostic evaluation of patients." (PMID 31534497, 2019). "Prognosis of low KLF5 /high BECN1 expression cohort was the worst compared with the three other cohorts (p=0.0099) which suggested that the level of KLF5/BECN1 axis was significantly associated with recurrence of prostate cancer." (PMID 31534497, 2019). "In this study, we tested whether and how KLF5 regulates angiogenesis in the context of PTEN loss in prostate cancer." (PMID 25896712, 2015). "Therefore, one mechanism for the upregulation of HIF1α by KLF5 loss in PTEN deficient or insufficient prostate cancer cells appears to be the activation of AKT." (PMID 25896712, 2015). "In the context of concurrent deletions of KLF5 and PTEN in human prostate cancer, our findings further suggest that during the development of human prostate cancer, KLF5 loss and PTEN loss cooperate to enhance tumor angiogenesis by upregulating HIF1α and VEGF, which remains to be examined." (PMID 25896712, 2015). "Moreover, interruption of Klf5 acetylation promoted tumor growth, accelerated cell proliferation, enhanced the formation of tumor organoids, and altered Smad4-knockout–associated genes in Pten-deficient prostate cancer." (PMID 38781024, 2024). "Thus, clinical evidence supports that KLF5 might play a role in prostate cancer progression and low KLF5 expression is associated with poor prognosis." (PMID 31534497, 2019). "Therefore, enhanced tumor angiogenesis represents another mechanism for how KLF5 insufficiency and deficiency could promote the development and progression of human prostate cancer." (PMID 25896712, 2015). "FOXM1 is a known major contributor to prostate cancer progression and its upregulation correlates with low disease-free survival, whereas KLF5 functions as a tumor suppressor and is downregulated in more advanced stages of cancer progression." (PMID 40115748, 2025). "In fact, Klf5 co-regulation of Srebf1 in the control of lipid biogenesis has been found in squamous and prostate cancer." (PMID 40250760, 2025). "In summary, this study defines Klf5 acetylation at K358 as a PTEN deficiency–induced PTM, which constrains prostate cancer growth by attenuating FGFR1 activation." (PMID 38781024, 2024). "KLF5 acetylation has a role in reprogramming cancer-associated fibroblasts and contributes to the synergism between AKT and CX3CR1 inhibitors in a prostate cancer model." (PMID 38781024, 2024). "In human prostate cancer samples, we found that Ac-KLF5 expression was significantly higher when AKT was activated, consistent with the findings in the GEMM." (PMID 38781024, 2024). "More important, we established a genetically engineered mouse model (GEMM) to conditionally interrupt Klf5 acetylation, providing a unique animal model to address the role of Ac-KLF5 in the progression of PTEN-deficient prostate cancer." (PMID 38781024, 2024). "We further measured TNF-α expression levels by IHC staining in the prostates of PBCrePten–/–Klf5KR/KR and PBCrePten–/–Klf5+/+ mice and confirmed that Klf5KR knockin significantly induced TNF-α expression in Pten-deficient mouse prostate cancer." (PMID 38781024, 2024).
prostate carcinoma (continued). "TGF-β induces KLF5 acetylation in prostate cancer, and Ac-KLF5 induced by TGF-β is essential for TGF-β to suppress cell proliferation and tumor growth." (PMID 38781024, 2024). "In our study to further understand how deacetylation of Klf5 in prostate cancer cells reprograms fibroblasts, 3 subclusters of fibroblasts were revealed by their distinct marker gene expression." (PMID 38781024, 2024). "In our study, interruption of KLF5 acetylation remodeled the communication between CAFs and prostate cancer cells, emerging as a pivotal factor enabling PTEN-deficient prostate cancer to overcome the progression barriers." (PMID 38781024, 2024). "This corroborates that the removal of KLF5 acetylation is a crucial event in the progression of prostate cancer." (PMID 38781024, 2024). "It is likely that the whole development of prostate cancer requires a rapid shift of KLF5 acetylation, which endows prostate cancer cells with plasticity and adaptation to different microenvironments." (PMID 38781024, 2024). "Interruption of Klf5 acetylation, on the one hand, signals iCAFs to release FGF9 via TNF-α; on the other hand, deacetylation of Klf5 induces CX3CR1 expression in prostate cancer cells." (PMID 38781024, 2024). "In our most recent study, Ac-KLF5 suppressed tumor growth in subcutaneous prostate cancer xenografts but stimulated bone metastatic lesions by promoting osteoclast differentiation." (PMID 38781024, 2024). "More recently, we found that the TGF-β/Ac-KLF5 axis also induces bone metastasis and drug resistance in prostate cancer." (PMID 36810084, 2023). "Downregulated KLF5 in prostate cancer activates STAT3, leading to immune escape and metastasis of tumors." (PMID 36761967, 2023). "For the remaining 4 drugs, we determined the killing specificity and IC50 values in PC-3 and DU 145 prostate cancer cells expressing KLF5, KLF5K369Q, and KLF5K369Q using the CCK-8 assay." (PMID 36810084, 2023). "Bone-borne TGF-β can induce the transcription factor KLF5 acetylation in advanced prostate cancer-mediated bone metastases." (PMID 38260135, 2023). "In summary, we adopted the recently developed spheroid invasion screening assay to identify FDA-approved drugs that target bone metastasis induced by acetylated-KLF5 in prostate cancer." (PMID 36810084, 2023). "We confirmed that, among the commonly used prostate cancer cell lines (LNCaP, C4-2B, PC-3, and DU 145), PC-3 cells expressed the highest level of KLF5." (PMID 36810084, 2023). "In prostate cancer cells, KLF5 collaborates with HDAC3 to inhibit Beclin1 transcription and reduce autophagy." (PMID 37391422, 2023). "In prostate cancer, KLF5 interacts with androgen receptor (AR) and contributes to cancer development stimulated by AR signaling." (PMID 37181807, 2023). "In the prevention mode, prostate cancer cells expressing Ac-KLF5-mimicking KLF5K369Q mutant (i.e., PC-3-KQ-Luc) were injected into mice via the caudal artery in the tail following a recently described procedure." (PMID 36810084, 2023). "Osteoclast differentiation is an essential mechanism for Ac-KLF5 to induce bone metastasis in prostate cancer." (PMID 36810084, 2023). "Recent studies show that KLF5 inhibits prostate cancer invasion through interactions with IGF1/STAT3 pathway." (PMID 38087142, 2023). "NTZ is a potential therapeutic agent for bone metastasis induced by the TGF-β/Ac-KLF5 signaling axis in prostate cancer and likely other cancers." (PMID 36810084, 2023). "In prostate cancer, higher levels of KLF5 expression and lower levels of KLF13 expression suggest that patients can achieve better outcomes with immunotherapy and chemotherapy." (PMID 36761967, 2023). "It has been demonstrated that KLF5 acts as a tumor suppressor in prostate cancer, esophageal cancer, and pituitary adenoma." (PMID 35836107, 2022). "The KLF5 gene is located on chromosome 13q.21 and genomic hybridization analysis has demonstrated its deletion in 39% of prostate cancer cases." (PMID 35317831, 2022).